TLR3 (toll like receptor 3)
Diseases named in the same sentence as TLR3 in open-access papers (continued):
Sharing a sentence is not in itself a finding about the gene and the disease.
liver fibrosis (continued). "The results showed that TLR3 deficiency caused severe clonorchiasis with increased parasite burden, exacerbated proinflammatory cytokine expression and liver lesions, promoted the TGF-β1/Smad2/3 pathway and myofibroblast activation, exacerbated liver fibrosis (compared to WT mice)." (PMID 37167198, 2023). "The present data indicated that BECs TLR3 deficiency resulted in significantly increased IL-6 and TNF secretion induced by CsEVs, which may be an important reason for more severe liver damage and liver fibrosis in TLR3-/- mice infected with C. sinensis." (PMID 37167198, 2023). "In addition, TLR9 expressed on HSCs can also be activated by DNA fragments released from hepatocytes, which aggravates the progression of liver fibrosis, while TLR3 and TLR7 signaling could impede liver fibrosis progression." (PMID 35990625, 2022). "However, it is not clear whether poly I:C also has inhibitory effect on liver regeneration in a model of liver fibrosis induced by chronic CCl4 treatment, and whether inhibition of liver regeneration by TLR3 also contributes to liver fibrogenesis." (PMID 20936107, 2010). "Taken together, TLR3 inhibit IL-6 and TNF production via p38/ERK signaling pathway, a phenomenon that resulted in the alleviation of C. sinensis-induced liver fibrosis." (PMID 37167198, 2023). "However, whether C. sinensis can activate the TLR3 pathway and the role of TLR3 in liver fibrosis caused by C. sinensis has not been extensively explored." (PMID 37167198, 2023). "For example, hepatocytes secrete exosomes during liver injury, which mediate the activation of Toll-like receptor 3 (TLR3) in HSCs and thus exacerbate liver fibrosis by enhancing interleukin-17A (IL-17) production by γδ T cells." (PMID 34234100, 2021). "Our study clarified the mechanism by which TLR3-p38/ERK regulated cytokine expression promoted inflammation and damage, and also found that TLR3 deletion leaded to increased activation of TGF-β/Smad pathway in C. sinensis-induced liver fibrosis." (PMID 37167198, 2023). "TLRs including TLR2, TLR3, TLR4 and TLR9 are expressed on hepatocytes, Kupffer cells, fibroblasts, neutrophils, dendritic cells and endothelial cells in the liver and activated in hepatic fibrosis liver tissue." (PMID 37122694, 2023). "TLR-3 bounded to poly I : C induces activation of NK cells which can destroy HSCs, and produces IFN-gamma to induce apoptosis and inhibit proliferation of HSCs leading to inhibition of liver fibrosis." (PMID 22114589, 2011). "Since type I IFN is known to inhibit HSC proliferation, it is plausible to speculate that activation of TLR3 may also directly block HSC proliferation via production of IFN-β, thereby contributing to suppression of liver fibrosis." (PMID 20936107, 2010). "In addition to TLR4, HSCs also express TLR3 and TLR9, which are related to liver fibrosis." (PMID 34071550, 2021). "TLR3 participates in the early stages of liver fibrosis but not during advanced liver fibrosis." (PMID 24904576, 2014).
myocarditis (19 papers, 2009 to 2025). Myocarditis is a condition that is characterized by inflammation of the heart muscle (myocardium). "Mutations in toll-like receptor 3 (TLR3) make people more vulnerable to enteroviral myocarditis and cardiomyopathy." (PMID 37456487, 2023). "TLR3 deficiency in mice with Coxsackie virus B3 (CVB3) infection increases viral replication during the acute period of myocarditis." (PMID 37113698, 2023). "Single-case or small cohort studies identified Interleukin 12 receptor subunit beta 1 (IL12RB1) variants and the TLR3 p.Pro554Ser variant as genetic susceptibility factors for myocarditis." (PMID 35877578, 2022). "Innate immunity against CVB is dependent on TLR3, as TLR3-deficient mice develop fulminant myocarditis and are unable to sustain high levels of IFN-I." (PMID 28973047, 2017). "Next, we compared heart function in TLR3- versus TRIF-deficient mice during acute CVB3 myocarditis by echocardiography." (PMID 22013485, 2012). "End systolic pressure (ESP) was significantly lower in TRIF- compared to TLR3-deficient mice during acute myocarditis (65 ± 4.5 versus 96 ± 4.7 mmHg, P < 0.05)." (PMID 22013485, 2012). "Our data showed that although TRIF-deficient mice developed similar myocarditis compared to TLR3-deficient mice, they had significantly worse cardiac function." (PMID 22013485, 2012). "Surprisingly, pressure-volume analysis of heart function showed that rIL-33-treated TLR3-deficient mice had significantly improved heart function during acute CVB3 myocarditis." (PMID 22013485, 2012). "Although TLR3- or TRIF-deficient mice developed similarly worse acute CVB3 myocarditis and viral replication compared to control mice, disease was significantly worse in TRIF compared to TLR3-deficient mice." (PMID 22013485, 2012). "As expected, there was a significant increase in viral replication and acute myocarditis at day 10 pi in TLR3- or TRIF-deficient mice compared to WT controls, confirming previous reports." (PMID 22013485, 2012). "Previous reports have found that increased myocarditis and HF in TLR3- or TRIF-deficient mice is due primarily to increased viral replication." (PMID 22013485, 2012). "Moreover, TLR3 deficiency resulted in high virus load and severe myocarditis in the mice infected with CVB3." (PMID 39348396, 2024). "Moreover, the deficiency of TLR3 led to an aggravation of acute myocarditis and an increased mortality in mice." (PMID 29538462, 2018). "We show in this study that high viral replication does not itself account for increased IL-33 levels in the heart during CVB3 myocarditis because similar amounts of viral replication occurred in TLR3- and TRIF-deficient hearts, but IL-33 levels were only increased in TRIF-deficient mice." (PMID 22013485, 2012). "To confirm that the increased IL-4 and decreased IFN-γ levels that we had observed in the heart of TLR3-deficient mice during acute myocarditis were due to a shift to a classic Th2 response, we examined markers of IL-4-driven alternative activation in the heart by qRT-PCR." (PMID 22013485, 2012). "Because IL-33-treatment was found to decrease cardiac function during acute CVB3 myocarditis in WT mice, we tested whether rIL-33 treatment of TLR3-deficient mice (that have a classic Th2 response) could worsen myocarditis." (PMID 22013485, 2012). "Additionally, administration of rIL-33 to Th2-skewed TLR3-deficient mice reduced cardiac dysfunction during acute myocarditis." (PMID 22013485, 2012). "Our observations suggest that genetic differences leading to changes in TLR3 function or expression could be linked to susceptibility to viral-induced myocarditis." (PMID 19122812, 2009). "Interestingly, overactivation of TLR3 is more closely associated with pathogenesis of myocarditis." (PMID 36016408, 2022).
myocarditis (continued). "In addition, the polarization of adaptive immunity is also affected by TLR3, as it has been shown that TLR3-deficient mice on the B6.129 background develop a IL-4-producing Th2 response profile during CVB3 myocarditis instead of the IFN-γ-producing Th1 phenotype observed in resistant B6.129 mice." (PMID 28973047, 2017). "Infection of mice with EMCV is known to lead to myocarditis, with severe inflammation of the heart and brain, and TLR3 signaling is crucial for the host response to EMCV infection." (PMID 37158982, 2023). "IL-4 deficiency in mice improves heart function during acute CVB3 myocarditis, suggesting that TLR3 prevents myocarditis by reducing viral replication and IL-4 levels in the heart." (PMID 37113698, 2023). "Recent animal studies have revealed that Toll-like receptor 3 (TLR3) can impede the progression from myocarditis to inflammatory DCM in coxsackievirus B3-infected mice by suppressing acute viral replication and reducing IL-4 levels in the heart." (PMID 37512058, 2023). "Additional research needs to be conducted to better understand the mechanism by which CHIKV infection elicits cardiac damage and myocarditis, given this apparent contradiction concerning TLR3 activation." (PMID 36016408, 2022). "During acute CVB3-induced myocarditis most of the plasma membrane and intracellular localized TLRs showed an enhanced gene expression, however, Tlr2, Tlr3, Tlr6, Tlr7, and Tlr9 displayed by far the highest increase of mRNA expression during acute disease." (PMID 29538462, 2018). "TLR3 is also important for restricting CV-B3 infections as TLR3−/− mice infected with CV-B3 were found to have increased myocarditis and mortality." (PMID 26784219, 2016). "Previously, TLR3- or TRIF-deficient mice were found to develop increased viral replication and acute myocarditis." (PMID 22013485, 2012). "During acute myocarditis, ejection fraction (EF) was significantly lower in TRIF- than TLR3-deficient mice (26% ± 2.8 versus 48% ± 4.7, P < 0.05)." (PMID 22013485, 2012). "To examine the effect of TLR3 versus TRIF deficiency on myocarditis, DCM, and HF, we used an autoimmune model of CVB3 myocarditis where mice receive infectious virus and heart proteins." (PMID 22013485, 2012). "For instance, a protective role for TLR3 has been demonstrated in a model of viral induced myocarditis." (PMID 19122812, 2009). "Instead, these patients often express variants in genes associated with inherited cardiomyopathies, suggesting that TLR3 signaling is not the sole determinant of CVB-induced myocarditis." (PMID 31117206, 2019). "Although a rare polymorphism in TLR3 was identified in a patient who developed CVB-associated myocarditis, genetic variants in TLR3 or other IFN-associated factors are not commonly found in patients with viral-associated myocarditis." (PMID 31117206, 2019). "Interestingly, merely the intracellular localized TLRs Tlr3, Tlr8, and Tlr9 demonstrated elevated gene expression also at the chronic stage of myocarditis (28 days pi CVB3)." (PMID 29538462, 2018). "Th2 cell-associated cytokine IL-33 could alleviate the severity of viral myocarditis in TLR3 knock-out mice, increase the percentage of Th2 cells, and prevent the progression from acute myocarditis to chronic myocarditis." (PMID 30176160, 2018). "Humans who develop myocarditis after enteroviral infections have increased frequencies of single nucleotide polymorphisms (SNPs) in TLR3 that render them less responsive to TLR3 ligands, and TLR3-/- mice are more susceptible to CVB infection and exhibit increased mortality and myocarditis." (PMID 26509685, 2015). "In addition, TLR3-expressing DCs are correlated with resistance to CVB-induced myocarditis." (PMID 28973047, 2017). "Potential targets of miR-146a are TLR3, TRAF6 and IRAK1/2/4; however, TLR3 and TRAF6 have recently been shown to be relevant to myocarditis." (PMID 39456716, 2024).
myocarditis (continued). "Based on these results, it appears that activation of TLR3 and TRIF inhibits CVB3 myocarditis in a similar manner." (PMID 22013485, 2012). "Previous reports had not described the type of Th2 response TLR3- or TRIF-deficient mice develop during CVB3 myocarditis, and since susceptibility to chronic autoimmune myocarditis is dependent on a Th2-type immune response, we were interested in determining whether a shift had occurred." (PMID 22013485, 2012). "Further evidence that TLR3 and TRIF have separate roles in regulating the progression from myocarditis to DCM was obtained by comparing acute and chronic heart function using pressure-volume relationships in WT and knockout mice." (PMID 22013485, 2012). "Although the mechanism has not yet been elucidated, the difference in cardiac function and survival/HF between TLR3- and TRIF-deficient mice suggests that TLR4-mediated TRIF may be responsible for reducing the negative cardiac effects of IL-33 in the heart during acute CVB3 myocarditis." (PMID 22013485, 2012). "So even though it appears as if BL/6 mice have higher levels of IL-4 and IFN-β during acute myocarditis (WT for TRIF−/−) compared to B6.129 mice (WT for TLR3−/−), this may only be an artifact of processing." (PMID 22013485, 2012). "Thus, our findings show the role of TLR3-expressing DCs in the activation and polarization of the CD4+ T lymphocyte response and indicate that they play a role together with other TLR3+ cells on the resolution of CVB3 infection, as these cells impair the development of myocarditis and pancreatitis." (PMID 28973047, 2017). "Although both knockout strains developed similarly worse acute CVB3 myocarditis and viral replication compared to wild-type (WT) mice, disease was significantly worse in the absence of TRIF compared to TLR3." (PMID 22013485, 2012).
colorectal cancer (18 papers, 2013 to 2026). A primary or metastatic malignant neoplasm that affects the colon or rectum. "Azacytidine is reported to induce anti-tumour effects through the activation of RNA sensors RIG-I/MAVS and the TLR3 pathways in ovarian, and colorectal cancers." (PMID 35998812, 2022). "The TLR3/cGAS‐STING‐IFN signaling has recently been reported to be disturbed in colorectal cancer due to deregulated expression of the genes involved." (PMID 31869529, 2020). "Constitutional loss of function (LOF) single nucleotide polymorphisms (SNPs) in pattern recognition receptors FPR1, TLR3, and TLR4 have previously been reported to predict oxaliplatin benefit in colorectal cancer." (PMID 30649440, 2019). "However, it is possible that TLR3 is also involved in the inflammatory cytokine production‐promoting mechanism induced by colorectal cancer EVs." (PMID 40326665, 2025). "Finally, a study found the strong expression of miR-3121-5p in gut mucosa cells of patients with colorectal cancer, which are characterized by increased signaling of toll like receptor 3 and 8, exacerbating inflammation and inducing tumorigenesis." (PMID 35453708, 2022). "Further studies are required to determine whether tumor necrosis in colorectal cancer tumors can activate TLR3 as well as determine the consequence of such activation on tumor progression." (PMID 28717003, 2017). "JUN is involved in pathways like Toll-like receptor 3 (TLR3) signaling and prolactin signaling and plays a role in transcriptional activation of USP28 in colorectal cancer." (PMID 40092686, 2025). "Previous studies have reported that the Toll-like receptor family members TLR3, TLR4, and TLR5 were up-regulated in colorectal carcinoma tissues." (PMID 23866094, 2013).
neuroblastoma (18 papers, 2009 to 2023). Neuroblastoma (NB) is the most common solid, extracranial childhood tumor. "A later study confirmed that PKR is activated by TLR3 signaling, since poly(I:C)-induced phosphorylation of PKR in human neuroblastoma cells was impaired in TLR3-deficient cells." (PMID 34305942, 2021). "Since high-grade Neuroblastoma, which are largely therapy resistant, are often characterized by Caspase-8 deficiency, we aimed to investigate whether TLR3 can induce an alternative programmed cell death pathway in the absence of Caspase-8." (PMID 34011952, 2021). "TLR3 expression in neuroblastoma was associated with the improving prognosis." (PMID 34094905, 2021). "Indeed, it has been demonstrated that TLR3 activation by Poly(I:C) synergizes with 13-cis-retinoic acid in the treatment of high-risk neuroblastoma, through the activation of retinoic acid receptor beta (RARβ)." (PMID 33147700, 2020). "A further pro-apoptotic mechanism linked to TLR3 activation was described in neuroblastoma." (PMID 33147700, 2020). "Next, we attempted to confirm whether this phenomenon also occurred at the endogenous TLR3 level in an EV-A71-permissive cell line SK-N-SH, which is a human neuroblastoma cell line susceptible to EV-A71 infection." (PMID 30563052, 2018). "Along this line, we have recently shown the therapeutic potential of targeting the Toll-Like Receptor 3 (TLR3) to trigger cell death in neuroblastoma." (PMID 37414800, 2023). "Until now, the clinical value of TLR3 has mainly been studied in adult cancers, and mostly in carcinomas, although the beneficial effect of a high level of TLR3 expression has also been established in Neuroblastomas." (PMID 37414800, 2023). "First, EV-A71 infection results in the reduction of the TLR3 protein level in human neuroblastoma SK-N-SH cells and TLR3-transfected HEK293 cells." (PMID 31787104, 2019). "TLR3 mRNA levels were analysed by semi-quantitative RT-PCR in the neuronal precursors Ntera-2clD/1, from which NT-2N cells are derived, and in a human neuroblastoma cell line (SK-N-SH)." (PMID 19247444, 2009). "It was previously demonstrated that RSV could infect microglia and Neuro-2a (N2a) mouse neuroblastoma cells in vitro, and the expression of Toll-like receptor 3 (TLR3)/Toll-like receptor 7 (TLR7) in RSV-infected N2a cells was time-dependent." (PMID 33953861, 2021). "Another recent report indicated expression of TLR-3 in a subset of neuroblastoma specimens, thereby opening a new avenue of therapeutic intervention for TLR family members in neuroblastomas." (PMID 24205354, 2013). "When TLR3 was activated in the Caspase-8 negative neuroblastoma cell line SH-SY5Y, cell death was accompanied by lysosomal permeabilization." (PMID 34011952, 2021). "However, it remains unknown whether TLR3 may serve as a therapeutic target in human neuroblastoma (NB)." (PMID 21861882, 2011). "In this respect, TLR3-induced LMP, which occurs independently of Caspase-8, could represent a novel therapeutic strategy for cancers which silence Caspase-8 expression, like for example neuroblastoma." (PMID 34011952, 2021). "However, aside from neuroblastoma, TLR3 role in childhood cancers has not been evaluated." (PMID 37414800, 2023). "Activation of TLR3 triggers the extrinsic apoptotic pathway with Caspase-8 as an apical caspase in the Caspase-8 positive, RIPK3 negative Neuroblastoma cell line, SK-N-AS6." (PMID 34011952, 2021).
rheumatoid arthritis (18 papers, 2011 to 2025). A chronic, systemic autoimmune disorder characterized by inflammation in the synovial membranes and articular surfaces. "In addition to TLR3, which was shown to be involved in the recognition of self-RNAs released from necrotic synovial fluid cells in rheumatoid arthritis patients, TLR4 has been implicated in the recognition of various DAMPs in different autoimmune processes." (PMID 29416536, 2018). "While TLR3 is mostly expressed intracellularly, cell surface TLR3 has been observed on human dendritic cells, macrophages, endothelial cells, and synovial fibroblasts of rheumatoid arthritis patients." (PMID 28529959, 2017). "Additionally, necrotic cells from synovial fibroblasts of rheumatoid arthritis patients stimulate the release of cytokines through TLR3 activation." (PMID 24130907, 2013). "On this topic, an increasing number of studies have emphasized the involvement of TLR4 and TLR3 in the development of arthritic conditions such as rheumatoid arthritis (RA) and osteoarthritis." (PMID 31028244, 2019). "Inflamed synovial joints in rheumatoid arthritis (RA) are rich in EV and extracellular RNA; besides, RNA released from necrotic synovial fluid cells can activate the TLR3 signaling in synovial fibroblasts (SFs) from patients with RA." (PMID 29434584, 2018). "In conclusion, circ-CBLB promotes macrophage polarization toward the M1 phenotype by regulating the TLR3/TRAF3 signaling pathway, thereby exacerbating the inflammatory response in rheumatoid arthritis." (PMID 40746530, 2025). "In rheumatoid arthritis, OIP5-AS1 was proposed to inhibit inflammatory response by suppressing the toll like receptor 3-nuclear factor kappa B pathway." (PMID 34261477, 2021). "Our results show that rheumatoid arthritis synovial fibroblasts (RASF) express a series of TLRs, including TLR2, TLR3, TLR4, and TLR9, with the predominant expression of TLR3." (PMID 24936783, 2014). "In patients with rheumatoid arthritis, the expression of TLR2, TLR3 and TLR7 is significantly enhanced in synovial fibroblasts." (PMID 24130907, 2013).